STAT1 (signal transducer and activator of transcription 1)
Diseases named in the same sentence as STAT1 in open-access papers (continued):
Sharing a sentence is not in itself a finding about the gene and the disease.
cancer (continued). "STAT1 is required for CIN-induced cell death, which is deficient in aggressive cancer cells due to chronic inactivation of this pathway." (PMID 39345336, 2024). "Increased levels of STAT1 phosphorylation at Ser-727 in cancer cells incubated with IFN-ɣ indicated IFN-ɣ pathway activation." (PMID 38528526, 2024). "In the study conducted by Zhao and colleagues on nasopharyngeal carcinoma, targeting HP1ß inhibited STAT1 activation via IFNγ, which led to lowered PD-L1 expression and, as such, enhanced cancer cell killing by CAR T-cells." (PMID 39519018, 2024). "HCV-1b core protein also induces miR-93-5p upregulation and inhibits the IFN signaling pathway by directly targeting IFNAR1, whereas the miR-93-5p-IFNAR1 axis regulates STAT1 phosphorylation, which plays a crucial role in cancer development." (PMID 39228892, 2024). "Cytotoxic CD8+ T cells secrete interferonγ (IFNγ), which inhibits SLC7A11 by activating the JAK/STAT1 pathway in cancer cells, thereby inducing ferroptosis in cancer cells." (PMID 39238647, 2024). "Since evidence suggests that the V protein acts catalytically to dismantle STAT-1 signaling, it is likely that the delivery of only small amounts of V protein will have dramatic effects on increasing NK cell lysis of cancer cells." (PMID 39205244, 2024). "Among the enriched genes, we identified known hits that are important for immune-mediated cancer killing, e.g., STAT1 and IFNGR2." (PMID 38678024, 2024). "The PD-L1 immune checkpoint is a major negative regulator of immune response and is overexpressed in cancer, and the IFNγ-STAT1 pathway mediates the expression of PD-L1." (PMID 39329063, 2024). "Our results indicated that the phosphorylation of STAT1 activated by TGFBR2 fulfilled a cancer-suppressing function in BC." (PMID 39525474, 2024). "In H1299 and A549 cells, TUR has been demonstrated to suppress STAT1 activity, which inhibits cancer development and triggers apoptosis." (PMID 38723038, 2024). "The biological term enrichment analysis of the mRNAs of this subnetwork revealed pathways associated with cancer, such as the enrichment of the GNAQ, STAT1 and AKT3 oncogenes in the MAPK signaling pathway." (PMID 38302900, 2024). "For example, responsible genes in the regulation of cancer cell survival and proliferation such as STAT1, STAT5A, CD44 and BCL2 are upregulated." (PMID 39056676, 2024). "The STAT1 signaling pathway has been shown to play a role in chemoresistance in multiple cancers, including PC." (PMID 39091910, 2024). "We introduce an imaging method that non-invasively tracks NK cell activation by cancer cells through the STAT1 protein." (PMID 39349746, 2024). "HP1β inhibition suppressed IFNγ-induced STAT1 activation, which reduced PD-L1 expression and enhanced cancer cell killing by CAR T-cells." (PMID 39519018, 2024). "The responsiveness of cancer cells to interferon-γ (IFNγ) was estimated by evaluating IFNγ-mediated induction of target genes, STAT1 phosphorylation, HLA expression, and cell growth suppression." (PMID 39095793, 2024). "Oxygen- and glucose deprivation decrease MHC class I antigens in cancer cells, causing them to become unresponsive to IFN-mediated cytotoxic effects due to a malfunctioning STAT1." (PMID 38216787, 2024). "In the present study, both STAT1 and STAT2 are highly expressed and activated in LSCC, and associated with immune cell infiltration, suggesting their pro-cancer function and potential immune microenvironment remodeling functions." (PMID 38191598, 2024). "Cancer cells harboring the unphosphorylated STAT1/unphosphorylated STAT2/IRF9 complex are more resistant to DNA damage-inducing chemotherapy than those lacking the complex." (PMID 38474078, 2024).
cancer (continued). "TUR limited breast cancer metastasis to lung tissue was contributed to reducingMMP-9, survivin, GSK-3, PI3K, AKT, NF-κB, and cyclooxygenase and STAT1 stimulation, thus limiting cancer progress and promoting apoptosis inA549 and H1299 cells." (PMID 38723038, 2024). "In conclusion, the anti-cancer effects of QFM combined with PD-1 inhibitor are mainly through inhibiting activation of STAT1/IDO1-mediated tryptophan-kynurenine pathway and down-regulating expression of PD-1." (PMID 38882349, 2024). "Upon stimulation with EGF, EGFR activity is known to induce IRF1 gene cascades, largely through STAT1 phosphorylation/activation, in other cancer cell lines." (PMID 38339304, 2024). "A 4-gene inflammatory signature, comprising CD8, PD-L1, LAG-3, and STAT1, was recently shown to be associated with a better overall response to ICB in various cancer types." (PMID 37342338, 2023). "The SNV percentage heatmap found that MAP3K5, STAT1, and MAP3K9 have the highest single-nucleotide mutation rates in pan-cancer." (PMID 36969076, 2023). "verified that IFN-γ treatment induces cancer cell ferroptosis through the STAT1/IRF1/ACSL4 axis in hepatocellular carcinoma." (PMID 38288118, 2023). "STAT1 has dual roles in both differentiation and proliferation; it also acts as a tumor suppressor and an oncogene in cancer." (PMID 37925498, 2023). "STAT signaling is one of the most well-characterized mode of PD-L1 induction in cancer cells, but IL-1β primarily signals though NFκB pathway, therefore, we were surprised to see an increase in p-STAT1 and p-STAT3 levels in HCC827 cells treated with IL-1β." (PMID 37985999, 2023). "The enhanced expression of cytokines and their receptors mainly result in the aberrant regulation of JAK1/2, STAT1, STAT3, STAT5, and STAT6, causing inflammation and cancer development, cancer recurrence, and decreased overall survival." (PMID 38094755, 2023). "The individual silencing of STAT3, STAT1 on cancer cells was much prominent to suppress the MDR activity." (PMID 38304256, 2023). "A number of recent publications supported that STAT1 signaling is a promising target for regulating the PD-L1 levels in cancer cells." (PMID 37931529, 2023). "From the functional annotation analysis, CDKN2A, VEGFA, PTGS2, and STAT1 were involved in cancer pathways (hsa05200; KEGG pathway)." (PMID 36765810, 2023). "This includes STAT1 and STAT3, which encode two STAT family transcription factors, both of which are involved in the maintenance of healthy and cancer stem cells, while STAT3 additionally has been proposed as a target for treatment in PM." (PMID 36740402, 2023). "The roles of STAT3 and STAT1 in this system agree well with the potential use of STAT proteins as targets in cancer therapy, as has been suggested and addressed in different studies and in clinical trials." (PMID 37830552, 2023). "Multiple oncogenic signaling cascades (EGFR, CXCR4, FASN, P-gp, β-catenin, GSK-3B, STAT1, JAK2, MUC1, etc) are hallmarks of cancer cells that are associated with drug resistance, tumorigenic potential, and metastasis." (PMID 37151801, 2023). "Collectively this observation suggests that MDSC augments early generation of drug resistance of cancer cells by IL-6/STAT1 and IL-10/STAT3 axis." (PMID 38304256, 2023). "Second, the top 100 STAT1‐correlated genes were extracted from the TCGA database and listed after analyzing the transcriptomic data in pan‐cancer." (PMID 36734611, 2023). "Studies of cancer cells and ex vivo–stimulated T cells detail how cross-regulation between STAT1 and STAT3 modulates target gene expression." (PMID 37272871, 2023). "Activation of the FGFR signaling inhibits IFNγ-induced STAT1 phosphorylation and the expression of PD-L1, thus protecting cancer cells from the cytotoxic effects of CD8+ T cells, thereby supporting resistance to anti-cancer therapies." (PMID 37190141, 2023).
cancer (continued). "The results showed that TIM-3 acted on the polarization of M2 macrophages of STAT1 (signal transcription and activator of transcription 1) to promote the antitumor effect of macrophages in malignant tumors." (PMID 36865498, 2023). "Recognizing that STAT1 generally exerts anti-cancer effects, efforts have been made to identify small molecules that can amplify the transcriptional effect of STAT1." (PMID 38022653, 2023). "In this study, we found that STAT1 can inhibit bone metastasis of CRC, providing new insight into the STAT1-mediated inhibition of cancer metastasis." (PMID 36593458, 2023). "Several studies have shown that the activation or expression of STAT1 is lost in cancer cells originating from various tissue types, and correspondingly has a positive correlation with the survival of patients." (PMID 36899018, 2023). "Silencing of STAT3/STAT1 resulted reduced MDR frequency in cancer cells, suggesting the involvement of both STAT signaling in MDSC-induced generation of chemo-resistance." (PMID 38304256, 2023). "Our observations have suggested that MDSC secreted IL-10/IL-6/IL-1β are the critical players modulating the drug resistance of cancer cells via STAT3/STAT1/NF-κB pathway." (PMID 38304256, 2023). "Decreased expression of IFNGR1 and STAT1 has demonstrated to decrease sensitivity of cancer cells to the immune response mediated by IFN-γ48–50." (PMID 37925508, 2023). "With the action of IFN-γ, the activation of JAK1/2 and phosphorylation of STAT1 increase the expression of IRF1 on cancer cells." (PMID 38288118, 2023). "Reduced IFN-α and IFN-γ stimulation of p-STAT1 was identified by phosphoflow cytometry in cancer patient peripheral blood lymphocytes compared to healthy controls." (PMID 37741983, 2023). "Conglomeration of all our observations has suggested that MDSC secreted IL-6/IL-10/IL-1β are the supreme players regulating the drug resistance of cancer cells via STAT1/STAT3/NF-κB pathway." (PMID 38304256, 2023). "These act directly on the surface receptors of cancer cells through the paracrine system, and the downstream pathways such as STAT1 and nuclear factor kappa b (NF-κB) pathways enhance the proliferation and drug resistance of cancer cells." (PMID 37056723, 2023). "Hsa_circ_0086735-miR-1296-5p-STAT1 axis in the network can promote cancer progression and resistance to tamoxifen." (PMID 37187897, 2023). "The role of STAT1 signaling in TME has been previously suggested in Renca monoclonal cancer model, where a high expression of inflammatory gene signature driven by STAT1 signaling in TIME is correlated with the tumors’ responsiveness to ICBs58." (PMID 37055410, 2023). "This interaction activates the signal transducer and activator of transcription 1 (STAT1) and causes STAT1-promoting cancer stemness." (PMID 38046195, 2023). "In IDC, we found that the mRNA levels of OAS1 and STAT1 were downregulated, which has also been reported in other cancers." (PMID 36765396, 2023). "Specifically, it has been reported that when PARP1 is aberrantly activated in cancer cells, it blocks phosphorylation of STAT1 and STAT3 via the poly(ADP-ribosyl)ation, ultimately reducing their transcriptional activity." (PMID 37190289, 2023). "STAT1 has also been identified to promote cellular adhesion, migration, and invasion in several cancers, including OvCa." (PMID 37173951, 2023). "In a similar manner knockdown of STAT1 in HCA-7 colony 29 cancer cells prevented from PD-L1 protein synthesis." (PMID 38102680, 2023). "The last focus of our study, STAT1, is widely established to regulate cell radiosensitivity in various cancers." (PMID 36061358, 2022). "Work in both normal and cancer cells demonstrated that IRF9 can assemble with unphosphorylated STAT1 and STAT2 to form the unphosphorylated ISGF3 (U-ISGF3) complex." (PMID 35244540, 2022). "It is known that lncRNA PLAC2 can regulate STAT1 activity, and STAT1 can regulate cancer cell viability by regulating the translation of XiaP and Bcl-xl." (PMID 35475470, 2022).
cancer (continued). "Although other STAT factors, such as STAT1 and STAT5, have also been associated with cancers of the upper aerodigestive tract, we focused our current exploration on STAT3, based on our previous findings." (PMID 34850540, 2022). "Those imply that PTH-AS expression in T47D cells, MCF7 cells, and A549 cells affects the expression of various genes and cancer properties via upregulation of STAT1." (PMID 35618021, 2022). "Drug screening and functional assays revealed that HSP90 controls protein stability of the nuclear transcription factor STAT1 in a variety of different cancer cells, thereby promoting subsequent gene expression of immune checkpoint molecules (IDO1 and PD-L1)." (PMID 36158677, 2022). "IRDS genes encode STAT1, as well as ISG15, which is overexpressed in diverse cancers and links chronic inflammation with DNA damage resistance." (PMID 35681561, 2022). "Our data indicate that cancer cells with high STAT1 activity act as leader cells during polyclonal collective invasion." (PMID 35606369, 2022). "Mechanistically, BEBT-908-induced ferroptosis led to the activation of the endogenous IFN-γ-STAT1 signaling pathway in cancer cells." (PMID 35399527, 2022). "One of the identified transcription factors, whose binding site was disrupted was STAT1 which has been established as a favorable prognostic marker in several types of cancers, including CRC." (PMID 35562597, 2022). "Our data indicated that LSECtin downregulates the expression of STAT1 through the circFBXL4/miR-146a-5p axis, which ultimately leads to increased expression of FN1/CHD4 resulting in an increased risk of cancer." (PMID 35821222, 2022). "We further characterised the relationship between STAT1 and PD-L1 expression using the publicly available cancer genome atlas (TCGA) database of HNSCC patients." (PMID 35595823, 2022). "Our data demonstrated that STAT1 inhibition efficiently abrogated IFN-γ-induced MDK activation in all examined cancer cell lines, suggesting that the IFN-γ-MDK transduction is dependent on STAT1 in cancer." (PMID 35747815, 2022). "Stat1 expression and activation were reduced in cancer cell and stromal cell compartments of Tyk2Δ/Δ tumors, respectively, whereas Stat3 expression and activation remained unchanged." (PMID 36185806, 2022). "Our results further delineate a mechanism by which increased production of IFN-α or IFN-γ facilitated cancer cells to evade genotoxic stress by activating the transcriptional factor STAT1." (PMID 35503721, 2022). "This study demonstrates that the interferon-β/STAT1 axis drives the collective invasion of cancer cells with sealed intercellular spaces, and that STAT1-activated cells drive polyclonal collective invasion through low-invasive sub-clonal cells." (PMID 35606369, 2022). "Downregulation of STAT1 compromised measured anti-cancer effects, which were both confirmed in the in vivo and in vitro models." (PMID 35692770, 2022). "Despite that, results of other clinical trials with high STAT1 expression in cancer tissues are worse than those with low STAT1 expression in the cancerous tissues." (PMID 36176415, 2022). "Previous studies have reported that STAT1 contributes to migration and invasion in a variety of cancer cell types." (PMID 35606369, 2022). "The JAK1/STAT1 pathway is the canonical cytokine-induced signaling that is constitutively active in cancer cells." (PMID 35997090, 2022). "This interaction activates intracellular signaling in cancer cells, including NF-κB, Smad, and STAT1/2 pathways." (PMID 35626102, 2022). "We previously demonstrated that the expression of PD-L1 in cancer cells was decreased by silvestrol, but the effect was indirect and mediated by translation regulation of STAT1, a transcriptional regulator of PD-L1." (PMID 35267483, 2022). "Next, we investigated the ability of the targeted Nluc-27.pepL to activate STAT-1/-3 pathways in cancer cell lines." (PMID 35200430, 2022).
cancer (continued). "Collectively, these results show that EPI enhances the anti-cancer effect of 125I treatment via the JAK/STAT1 pathway." (PMID 35692770, 2022). "The findings of this study demonstrate that the INFB/STAT1 axis promotes the collective invasion of cancer cells with sealed intercellular spaces." (PMID 35606369, 2022). "This was motivated by recent observations that STAT1 expression can be increased by various cancer drugs." (PMID 35089788, 2022). "In all the carcinoma and hematopoietic cancer networks, STAT1 and STAT3 interact with a similar panel of proteins, including MTOR, SRC and EGFR." (PMID 35229974, 2022). "Further results noted were that miR-145-5p expressed genes mimic the gene expression of STAT1, a downregulation of IRF7 was noted in the GBC, and an activation of STAT1 was significantly noted in carcinoma cells of the gallbladder." (PMID 35035811, 2022). "Among the major Que-related pathways identified by KEGG, the pathways were mainly associated with the cancer pathway and PI3K-Akt signaling pathway; however, JAK/STAT1 signaling pathway ranked fourth among the pathways screened for immunity to Que." (PMID 34838003, 2021). "In various cancers, TYK2 overexpression or GOF mutations lead to STAT1 or STAT3 activation and upregulation of anti-apoptotic proteins, including B-cell CLL/lymphoma-2 (BCL-2) and myeloid cell leukaemia-1 (MCL-1)." (PMID 34439323, 2021). "Stat1 knockdown increased the cleavage of caspase-3 in cancer cells treated with cisplatin for 24 h." (PMID 34685622, 2021). "The genetic and pharmacological Stat1 inhibition interfered with these pro-angiogenic effects, dampening the crosstalk between cancer and endothelial cells." (PMID 34943903, 2021). "For this reason, an understanding of the stage-dependent mechanisms of STAT1 in cancer is necessary for the use of this molecule in clinical diagnosis." (PMID 34299314, 2021). "By facilitating the expression of NOTCH target genes in a STAT1-dependent manner, the stromal interaction with cancer cells drove the expansion of CSCs and, consequently, resistance to chemotherapy." (PMID 34298736, 2021). "Our observations are in good agreement with previous findings in cancer cells, showing that particularly the involvement of STAT1 activation is responsible for proteomic remodeling by IL-27." (PMID 33871355, 2021). "Since cancer cells also drive the expression of PD-L1 mRNA via the IFN-/JAK/STAT1 signaling pathway." (PMID 34211835, 2021). "Along similar lines, exosome transfer from stroma to cancer cells, was shown to drive RIG-I > STAT1-dependent signaling while promoting cancer stemness and therapy resistance." (PMID 34571733, 2021). "Since IFNγ strongly induces NLRC5 gene expression, further studies in normal and cancer cells are needed to resolve the conundrum of STAT1-mediated gene activation and EZH2-mediated epigenetic repression of the same target genes." (PMID 33671123, 2021). "A prominent mechanism linking the IFN-γ/STAT1 signaling pathway to cancer progression is the abrogation of apoptosis." (PMID 34784299, 2021). "Cancer cells express protocadherin 7 (PCDH7), promote carcinoma-astrocyte gap junctions, which then induces IFNα and TNF production and activation of STAT1 and NF-κB pathways in cancer cells to support brain metastasis." (PMID 33442395, 2021). "The STAT1 signaling can also be crosstalk with other signaling such as transforming growth factor-β signaling involved in cancer cell behavior." (PMID 33834023, 2021). "Restricted cell cycle genes in interferon-inducible pathways include antiviral and anti-cancer activity (Ifit1 and Ifit2) and pro-inflammatory reactions recruiting immune cells to target cells (genes Stat1 and Unc5cl)." (PMID 34202278, 2021).